ENO1 (enolase 1)
Diseases named in the same sentence as ENO1 in open-access papers (continued):
Sharing a sentence is not in itself a finding about the gene and the disease.
tumor (continued). "The reduced phosphorylation of ENO1 led to decreased phosphorylation of PI3K and Akt, which is further linked to the decline in cell proliferation and tumor progression." (PMID 32795333, 2020). "Although the special functions of ENO1 in some tumors have been well revealed, the role of exosome-derived ENO1 in the regulation of tumor progression, particularly in HCC, is incompletely clarified." (PMID 33184263, 2020). "Cappello and colleagues observed increased frequency of ENO1-expressing MDSCs in the blood of PDA patients compared to healthy donors as well as tumor-bearing KC mice compared to the age-matched littermates (control mice)." (PMID 31652904, 2019). "Previous studies have shown the involvement of ENO1 in tumor progression through regulating glycolysis in lung cancer." (PMID 31767835, 2019). "Enolase 1 (ENO1), as a glycolysis enzyme, performs pivotal role in glucose metabolism and contributes to tumor progression of numerous cancers." (PMID 31767835, 2019). "Our work is to uncover the regulatory mechanism circ-ENO1 on its host gene ENO1 and its function in glycolysis and tumor progression." (PMID 31767835, 2019). "The results based on GSE79973 and TCGA data analysis showed that the expression of ENO1 was significantly higher in tumor tissues compared with that in normal tissues." (PMID 31889896, 2019). "ENO1 catalyzes the penultimate step in glycolysis, but is also involved in regulation processes, such as inflammatory cell recruitment and tumor suppression." (PMID 30876387, 2019). "Rescue assays indicated that circ-ENO1 promoted glucolysis and tumor progression of LUAD through miR-22-3p/ENO1." (PMID 31767835, 2019). "Although ENO1 was considered to be a potential tumor marker using proteomics in cell lines and tissues, few studies were carried out in the peripheral blood of PDAC patients." (PMID 29483925, 2018). "Although the majority of ENO1 is cytosolic and promotes tumor pathogenesis and progression, ENO1 is also present on the cell surface as a plasminogen receptor to promote cell migration and cancer metastasis." (PMID 30242159, 2018). "These ENO1-specific TILs were frustrated in their Th1 and Th17 effector functions by ENO1-specific Tregs, and were much more representative in the marginal area than within the tumor, where Tregs were more numerous." (PMID 29462900, 2018). "When anti-ENO1 detection was combined with other two tumor protein biomarkers (CEA and CYFRA 21-1), the sensitivity of NSCLC increased to 84%." (PMID 28456790, 2017). "ENO1 expression was increased in tumor tissues (high expression rate: 13% in non-tumor tissues and 69% in tumor tissues)." (PMID 28548950, 2017). "ENO1 is a glycolytic enzyme, which has been found to play other roles in inflammation, tumor suppression, monocyte and mast cell differentiation." (PMID 28525970, 2017). "Recent study also shows that ENO1 activates pericellular plasminogen, resulting in accelerating degradation of the extracellular matrix and elevation of invasion and metastasis of tumor cells." (PMID 28415822, 2017). "ENO1 has been found to play other roles in inflammation, tumor suppression, monocyte and mast cell differentiation." (PMID 28525970, 2017). "The activated networks (HIF1A, ESRRA, ESRRG) had many proteins that were increased in tumor tissues that overlapped between the three targets, such as ENO1/ENO2, ALDOA, and LDHA." (PMID 27128972, 2016). "A clinical trial amongst Chinese patients revealed enolase 1 protein levels in tumor tissues and circulating plasma samples of NSCLC patients to be increased to suggest this glycolytic enzyme to be of diagnostic utility." (PMID 27602772, 2016). "Enolase-1 expressions in glycolytic process at hypoxia favor the tumor cells to solve their energy requirements." (PMID 27110560, 2016).
tumor (continued). "We subsequently examined the expression of HSP 70 and Eno-1 in resected HCC specimens by immunohistochemistry and found that both HSP 70 and Eno-1 are expressed by HCC tumor cells, but minimally expressed by paratumoral normal hepatocytes." (PMID 26918350, 2016). "In conclusion, our study has provided comprehensive proteomics, biochemical and functional data to demonstrate that ENO1 is a master regulator of tumor metabolism." (PMID 26734996, 2016). "ENO1 silencing resulted in a profound reduction of tumor volume compared to that observed when control cells were injected." (PMID 26734996, 2016). "In tumor cells, the expression of Eno-1 was up-regulated and supported anaerobic proliferation (Warburg effect), driven tumor invasion through plasminogen activation and extracellular matrix degradation." (PMID 26918350, 2016). "In vivo, blockade of ENO1 by two specific anti-ENO1 mAbs reduced tumor spreading in different mouse xenograft tumor models." (PMID 25860938, 2015). "This ruled out the possibility that the inhibitory effect of the anti-ENO1 mAb on migration is due to interference with the growth of tumor cells." (PMID 25860938, 2015). "Gene knockdown in the xenografts was confirmed by QPCR on total RNA extracted from frozen tumor tissue, which reached more than 50% for all genes except ENO1." (PMID 25932951, 2015). "The level of anti-ENO1 Ab in tumor-implanted mice with ENO1-immunization was reduced significantly during the exponential growth period of both tumors, while the level of anti-OVA Ab in tumor-implanted mice with OVA-immunization remained at a similar level." (PMID 26551021, 2015). "There is a negative correlation (r = −0.13) between the expression of ENO1 in tumor sections and the blood level of anti-ENO1 Ab." (PMID 26551021, 2015). "To clarify the role of Treg cells in the reduction of anti-ENO1 Ab, we first evaluated the amount of Treg cells in the tumor-implanted mice." (PMID 26551021, 2015). "No significant suppression on the Ag-dependent proliferation of ENO1- or OVA-specific CD4+ T cells was observed using Treg cells isolated from the spleens of tumor-free mice." (PMID 26551021, 2015). "We first investigated the influence of tumor mass on the level of adoptively transferred anti-ENO1 Ab." (PMID 26551021, 2015). "Vaccination of ENO1 in transgenic mice that spontaneously develop PDAC delays tumor progression and enhances survival of mice." (PMID 26551021, 2015). "We have previously reported that among patients with non-small-cell lung carcinoma (NSCLC), those with tumor cells expressing a higher level of ENO1 have poorer DFS and OS." (PMID 26551021, 2015). "As early as day 14 after tumor injection, anti-ENO1 mAb-treated mice emitted a significantly reduced number of photons compared to the control group, as evaluated by IVIS spectrum technology." (PMID 25860938, 2015). "In a previous study, ENO1 was upregulated and activated by several glucosetransporters and glycolyticenzymes that contribute to the Warburg effect in tumor cells." (PMID 25951350, 2015). "We conducted experiments with murine tumor models to elucidate the potential molecular and cellular mechanisms responsible for the modulation of anti-ENO1 immune response in cancer patients in our clinical studies." (PMID 26551021, 2015). "The hazard ratio, which was adjusted in the multivariate Cox regression model for tumor progression, is lower in patients with a higher increase of anti-ENO1 Ab (P = 0.011), adenocarcinoma subtype (P = 0.017) and a small tumor volume (P = 0.017)." (PMID 26551021, 2015). "Further, ENO1 has been shown to promote cell proliferation, cycle progression, migration, and invasion, which suggests that ENO1 functions as an oncogene in tumor pathogenesis." (PMID 25887760, 2015).
tumor (continued). "To determine the possible influence of ENO1 released by tumor cells on the detected level of anti-ENO1 Ab in the circulation, we first estimated the amount of ENO1 released by 1 × 106 tumor cells using a competitive ELISA assay." (PMID 26551021, 2015). "Secondly, anti-ENO1 Ab can be absorbed and bound to surface-expressed ENO1 in tumor cells, leading to a reduction of blood anti-ENO1 Ab in cancer patients." (PMID 26551021, 2015). "Flow-cytometry, using specific 72/1 mAb, revealed that ENO1 was expressed on the surface of the majority of the tumor cell lines tested, namely PT45, MIA PaCa-2, Hs766T, T3M4, CFPAC-1, and L3.6pl." (PMID 25860938, 2015). "Recently, we demonstrated that ENO1 on the surface of tumor cells mediates activation of proteolytic enzymes and promotes degradation of the extracellular matrix." (PMID 26551021, 2015). "Post-mortem observations confirmed a reduced number of tumor masses in anti-ENO1 mAb-treated mice compared to control mice." (PMID 25860938, 2015). "ENO1 from necrotic cancer cells is released to tumor-infiltrating cells, such as lymphocytes, dendritic cells, and macrophages during tumor growth." (PMID 26551021, 2015). "In this study, we demonstrated that the anti-ENO1 immune response was suppressed during tumor growth, and the tumor volume in ENO1-immunized mice was smaller than that in control mice." (PMID 26551021, 2015). "Ex vivo analysis of PANC-1 cells from a liver metastasis showed that the surface expression of ENO1 was higher compared to the parental cells from the primary tumor." (PMID 25860938, 2015). "Consistently, we observed that ENO1-silenced groups treated with DDP exhibited larger tumor growth inhibition than the control groups treated with DDP." (PMID 25951350, 2015). "The detected level of anti-ENO1 Ab in mice with large tumor sizes was significantly less than that in mice with small tumor sizes on day 4 after Ab transfer in both tumor models." (PMID 26551021, 2015). "In conclusion, ENO-1 expresses different proteins that can be localized either in the nucleus as a tumor repressor or in the cytosol as a glycolytic enzyme or, finally, at the cell surface, where it promotes invasiveness and metastasis." (PMID 25621294, 2014). "Pancreatic ductal carcinoma (PDAC) is another tumor, characterized by increased cell surface expression of ENO-1." (PMID 25407528, 2014). "In tumor cells, ENO1 is upregulated and activated by several glucose transporters and glycolytic enzymes that contribute to the Warburg effect." (PMID 24650096, 2014). "As MMP2 and 9, substrates in the plasmin proteolytic cascade, are involved in the degradation of ECM and invasion of tumor cells, the effect of blocking ENO1 on the activation and activity of MMP2/9 was next examined." (PMID 23894455, 2013). "We next investigated the effect of blocking ENO1 on tumor bone metastasis in the third animal model." (PMID 23894455, 2013). "Nevertheless, adoptively transferred ENO1-specific Ab efficiently accumulated at the s.c. site of tumor, suggesting the potential application of delivering therapeutic agents to tumors with ENO1-specific Ab." (PMID 23894455, 2013). "ENO1, HSP60, KRT8, PDI, TCRβ, TUΒΒ, and VIME were identified in the tumour cell lines using 2-D WB, and immunoprecipitation verified that ENO1, HSP60, KRT8, and TUBB were expressed and citrullinated in these cell lines." (PMID 24099319, 2013). "Fluorescence-labeled ENO1-specific Ab accumulated at the s.c. tumor following i.v. injection, indicating that the ENO1-specific Ab can effectively bind to LLC/luc tumor and delay lung metastasis." (PMID 23894455, 2013). "Patients with high ENO1 expression also had a poor prognosis with greater tumor size, poor nodal status, and a shorter disease-free survival." (PMID 22014164, 2011). "Tumor weight was found to be significantly reduced in ENO1 and HIF1α siRNA treated mice with respect to its control group." (PMID 21754983, 2011).
tumor (continued). "Previous histochemical studies conducted on tumor samples and normal tissues have reported three expression patterns of ENO1 gene products: cytoplasm, nuclei and both nuclei and cytoplasm." (PMID 20886042, 2010). "The loss of one allele seems either to be compensated in these cells, or the levels of ENO1-mRNA in the aggressive Stage 4 tumours are suppressed by a different mechanism in the 1p-intact Stage 4 tumours." (PMID 16359544, 2005). "Our studies indicate that ENO1 has tumour suppressor activity and that high level of ENO1 expression has growth inhibitory effects." (PMID 16359544, 2005). "Therapeutic targeting of extracellular ENO1 with HuL001 may disrupt these tumor-supportive stromal activities and help overcome drug resistance in MM." (PMID 42122262, 2026). "Moreover, targeting surface ENO1 significantly increased the therapeutic response to radiotherapy and delayed tumor regrowth by increasing antitumoral M1 macrophages and cytotoxic CD8+ T cells infiltration within TME." (PMID 41629269, 2026). "Targeting surface ENO1 with HuL001, a first-in-class humanized antibody, significantly reduced glycolysis, decreased extracellular lactate accumulation, reprogrammed macrophage polarization and inhibited tumor growth and distant metastasis." (PMID 41629269, 2026). "Our findings demonstrated that soluble ENO1 could drive GBM malignancy by regulating tumor cell proliferation, migration, and invasion through an autophagy-dependent secretory pathway." (PMID 41353343, 2025). "Preclinical studies demonstrate that targeting ENO1 using antibodies, small molecule inhibitors, DNA vaccines, or gene knockdown can suppress tumor growth, invasion, metastasis, and chemoresistance and may enhance the efficacy of chemotherapy." (PMID 41373732, 2025). "Based on these findings, targeting MDSC through PI3Kγ inhibition in conjunction with ENO1 DNA vaccination could work synergistically to combat tumor growth in a B-cell-dependent immune response." (PMID 41190066, 2025). "Moreover, the glycolytic genes HK2, GAPDH and ENO1 showed elevated expression levels in INSS stage 4 tumours when compared to stage 1 tumours, highlighting the increasing energy demands associated with cancer metastasis." (PMID 41420301, 2025). "This suggests that RARS1 may protect LIHC cells from ferroptosis through its regulation of ENO1 activity, thereby contributing to tumor cell survival." (PMID 41451236, 2025). "Beyond its role in glycolysis, ENO1 also interacts with choline kinase alpha (CHKα), a key enzyme in choline metabolism, stabilizing it and thereby promoting choline phospholipid metabolism and tumor cell proliferation." (PMID 40248198, 2025). "This spatial co-localization implicates ENO1 as a key mediator of tumor cell-macrophage crosstalk." (PMID 41353343, 2025). "Interestingly, the same phosphorylation site of ENO1 at serine 419 was found to be a tumor-specific marker in TN BC progression." (PMID 40894036, 2025). "Notably, we observed the same phosphorylation site of ENO1 at serine 419, previously reported as a tumor-specific marker in TN BC progression, highlighting the potential of plasma EV markers to reflect key candidate markers studied in cells or tissue." (PMID 40894036, 2025). "Inhibition of ENO1-regulated mitophagy sensitizes tumor cells to apoptosis." (PMID 39828712, 2025). "Since ENO1 is expressed on the tumor cell surface as a whole protein, inducing CD4+ T cells, the vaccine may also induce citENO1-specific B cells, resulting in antibody-dependent cellular cytotoxicity (ADCC)." (PMID 40573960, 2025). "The result showed that ENO1 was highly expressed and differentially expressed in tumor cells, suggesting that tumor-intrinsic ENO1 may contribute to the immune evasion of BC (Additional file2A-D)." (PMID 40665335, 2025). "The protein levels of TPI and ENO1 were significantly decreased in the HPD knockdown tumor tissues." (PMID 40491422, 2025).
tumor (continued). "Because the PI3K/AKT and AMPK/mTOR signaling pathways are classical pathways involved in energy metabolism, we next analyzed tumor samples from the TCGA database and found that patients with high expression of ENO1 (a key enzyme in glycolysis) presented higher glycolysis-related scores." (PMID 41168198, 2025). "The results showed specific patterns of expression for both ITIH2 and ENO1, suggesting that these proteins may play important roles in tumor development." (PMID 40005870, 2025). "Additionally, insights into tumor metabolism, such as the moonlighting role of enolase-1 in promoting phospholipid metabolism and proliferation, highlight the diverse functional landscapes AI models must implicitly learn from image data." (PMID 40994958, 2025). "ENO1 is frequently overexpressed in various cancers, driving tumor progression through mechanisms including promotion of glycolysis (Warburg effect), enhanced proliferation, inhibition of apoptosis, facilitation of invasion and metastasis, and adaptation to hypoxic microenvironments." (PMID 40859388, 2025). "Additionally, the role of metabolic enzymes in cancer, such as the moonlighting function of enolase-1 in promoting choline phospholipid metabolism and tumor proliferation, underscores the complexity of cancer biology." (PMID 40457491, 2025). "Moreover, ENO1 expression was examined in tumor tissues, and the results uncovered that Esc suppressed ENO1 accumulation in a concentration-dependent manner compared with the Ctrl group." (PMID 40740998, 2025). "Importantly, genetic and pharmacological inhibition of ENO1 sensitizes tumors to anti-tumor immunity and synergizes with anti-PD-L1 therapy." (PMID 40665335, 2025). "Among them, ENO1, as a glycolytic enzyme, can play a tumor-promoting role in a variety of tumors, which may indicate that the type B burn patients identified in this article have a poorer prognosis." (PMID 40655111, 2025). "Mechanistically, this co-expression pattern suggests a potential therapeutic strategy: targeting ALDOA/ENO1-dependent glycolysis could disrupt tumor metabolic reprogramming." (PMID 41049005, 2025). "Additionally, ENO1 promotes the M2 polarization of TAMs through glycolysis‐dependent and independent mechanisms, which supports tumor progression." (PMID 41328768, 2025). "The results highlight tumor-intrinsic ENO1 as a critical regulator of tumor immune evasion in BC." (PMID 40665335, 2025). "Furthermore, inhibiting ECM1 or utilizing the ENO1‐targeting inhibitor phosphonoacetohydroxamate (PhAH) significantly restores tumor cell sensitivity to ENZ." (PMID 39563492, 2025). "Moreover, treatment with 2-DG reversed the functional phenotypic changes induced by ENO1, further confirming that ENO1 regulated tumor stemness-related malignant phenotypes through glycolysis." (PMID 41168198, 2025). "The vivo experiments further confirmed that circ-ENO1 promoted tumor growth and metastasis." (PMID 40296917, 2025). "Furthermore, increased levels of tumor-infiltrating CD8+ T cells were demonstrated in ENO1-KO tumors through IHC staining, mIHC, and flow cytometric analysis." (PMID 40665335, 2025). "Integrated analysis of scRNA-seq and stRNA-seq revealed spatial co-localization of ENO1-high regions with TAM-enriched zones, providing histological evidence that ENO1 overexpression in GBM tissues is correlated with increased M2-polarized TAMs infiltration within tumor stroma." (PMID 41353343, 2025). "Translating these findings to GC, combinatorial strategies targeting ALDOA/ENO1 with immunotherapy may synergize by reversing macrophage-mediated immunosuppression, as ALDOA/ENO1 expression correlates with tumor-associated macrophage infiltration." (PMID 41049005, 2025). "ENO1 can promote tumor progression by interacting with and promoting AKT phosphorylation." (PMID 40533767, 2025).